STAT3 (signal transducer and activator of transcription 3)
Diseases named in the same sentence as STAT3 in open-access papers (continued):
Sharing a sentence is not in itself a finding about the gene and the disease.
tumor (continued). "Mechanistic studies have shown that the miR-197-mediated CKS1B/STAT3 axis plays a role in tumor progression and is regulated by multiple oncogenes (Bcl-2, c-Myc, and cyclin D1) and that PD-L1 is a putative biomarker of this axis." (PMID 33102238, 2020). "Recently, many studies reported that STAT3 is involved in the response of tumor cells to radiotherapy." (PMID 32733808, 2020). "STAT3 can not only increase the expression levels of miRNAs in tumor cells but also repress their levels (e.g., miR-200c and miR-145-5p) during cancer stem cell (CSC) growth." (PMID 33023006, 2020). "In inflammatory and tumor microenvironment, TAMs can produce cytokines such as IL-6/IL-17/IL-23 to induce the tumor initiation and progression via the NF-κB or STAT3 signaling pathway." (PMID 33201893, 2020). "miR-182-5p is a well-described oncomiR that, in HGG, is known to promote the proliferative and invasive capacities of tumor cells through the modulation of either STAT3 or NF-κB signaling pathways." (PMID 33287106, 2020). "IL-6 then triggers the signal transducer and activator of transcription 3 (STAT3) pathway in immune cells, stromal cells, and tumour cells." (PMID 33081785, 2020). "Researchers have observed that macrophage-driven efferocytosis of PCa in vitro activated Stat3 and NF-κB (p65) signaling to stimulate the expression of the pro-inflammatory cytokine CXCL5, whose deficiency reduced tumor progression." (PMID 32346605, 2020). "STAT3, as a transcription factor, plays an important role in tumor cell proliferation and progression." (PMID 32576206, 2020). "Since STAT3 phosphorylation is widely known for its role in proliferation, differentiation and apoptosis of various tumour cells, here, we also observed the phosphorylation levels of STAT3 in K1 and IHH4 cells." (PMID 32285621, 2020). "The examination of molecular pathways demonstrates that anti-tumor compounds are able to enhance the generation of reactive oxygen species (ROS) to modulate the expression of STAT3." (PMID 32545648, 2020). "We devoted a section to examining the relationship between anti-tumor compounds and the STAT3 signaling pathway in GC cells." (PMID 32545648, 2020). "The converging of two pathways resulting in the activation of NF-KB transcription factor, HIF-1α) and signal transducer and activator of transcription 3 (STAT3) in tumor cells." (PMID 33062602, 2020). "In summary, the inhibition of STAT3 in tumor cells results in a decrease in the E6 and E7 oncoproteins." (PMID 33076315, 2020). "In fact, STAT3 is itself known to contribute to epigenetic silencing via the DNA methylation of tumour suppressor genes." (PMID 32731620, 2020). "In acquired immune resistance, TIL-secreted IFN-γ and tumor antigen-specific T-cells mediate PD-L1 upregulation after tumor antigen recognition, and this functions as a tumor escape mechanism that uses constitutive oncogenic signaling, such as c-Jun and STAT3." (PMID 33322522, 2020). "Their potential for tumor initiation was shown in prostate cancer, where EVs isolated from tumor cells were able to upregulate the pro-survival protein STAT3, converting normal into malignant epithelial cells." (PMID 32485907, 2020). "CUEDC2 regulates the phosphorylation of STAT3 by regulating the stabilization of the SOCS1 or SOCS3 protein in tumor cells." (PMID 32393737, 2020). "In summary, we demonstrated that SH003 inhibits tumor growth through autophagic cell death mechanisms initiated by ER stress and represses STAT3 and G9a." (PMID 32879309, 2020). "OOE modulated ERK/Src/STAT3 activation and regulated STAT3-downstream genes related with tumor development." (PMID 32422890, 2020). "Some antitumor drugs, such as targeting microtubule paclitaxel, have been proved to inhibit activation of STAT3 to induce tumor cells apoptosis." (PMID 32576206, 2020).
tumor (continued). "The Stat3 pathway plays a key point in mediating the crosstalk between tumor cells and immune cells to provoke tumorigenesis and immunosuppression, since its constitutively activation mutually propagates among different cell subsets in the TME26,27." (PMID 33288772, 2020). "Previous data indicate that the Signal and Transducer of Activation 3 (STAT3) transcription factor is a hub for multiple signaling pathways which mediate tumor progression and immune functions." (PMID 33173024, 2020). "Most importantly, STAT3 plays a major role in maintaining stemness and promoting tumor survival and invasion while suppressing anti-tumor immunity." (PMID 33489908, 2020). "The in-vivo assays further revealed that circ_0043800 promoted HB tumor growth by up-regulation of Gli2 and STAT3." (PMID 32493490, 2020). "Bazedoxifene has been shown to suppress STAT3 activation through IL-6, inhibit tumor growth in a murine model of rhabdomyosarcoma, a soft-tissue sarcoma, and inhibit the proliferation of IL-6 dependent cell lines." (PMID 32765502, 2020). "STAT3-MB + UTMC (n = 7) reduced tumor growth compared to that in untreated control (n = 8) and STAT3-MB-mut + UTMC-treated mice (n = 7)." (PMID 33206698, 2020). "Some studies have shown that compared to normal cells, the 705 site of the C-amino terminal tyrosine in STAT3 is continuously and abnormally activated in about 70% of tumor cells." (PMID 32784629, 2020). "Based on all findings, Gli2-induced circ-STAT3 served as a ceRNA against miR-29a/b/c-3p to elevate STAT3 and Gli2 expression, thus facilitating cell proliferation, invasion, migration, stemness and tumor growth in HB." (PMID 32493490, 2020). "Polarization of macrophages towards the cancer-promoting M2 phase is stimulated by tumor cell-derived sEVs: breast cancer-derived sEVs induce M2 polarization of macrophage via glycoprotein 130/STAT3 signaling, resulting in IL6 secretion." (PMID 32015297, 2020). "Many tumor viruses such as hepatitis B virus, human papillomavirus, human T-lymphotropic virus type 1, Epstein–Barr virus also activate STAT3 by distinct mechanisms." (PMID 32824207, 2020). "This anti-tumor activity partially emanates from the inhibitory effect of glycitein on the expression of STAT3." (PMID 32545648, 2020). "For example, in colorectal cancer, tumor growth and niche inflammation are both attenuated by the dual inhibition of IGF-1R signaling and the STAT3 pathway, resulting in much smaller tumor sizes in both primary and metastatic tumors." (PMID 33511137, 2020). "STAT3 activation in the subcutaneous tumor tissue was also reduced following epimedokoreanin B administration." (PMID 32256354, 2020). "We identified Stat3, Irf7, Cox2, and Ifnβ as being up-regulated, while Il1β and Il12α show down-regulation under tumor condition." (PMID 32668709, 2020). "In the TME, macrophages, neutrophils and CAFs are the major cell types that secrete IL-6 and IL-1β; they are also responsible for STAT3 activation in tumor cells." (PMID 33153193, 2020). "The oral administration of KCP10043F decreased tumor growth in an A549 xenograft mouse model, as associated with the reduced phosphorylated STAT3, survivin, Mcl-1, and Bcl-2 expression and increased TUNEL staining and PARP cleavage in tumor tissues." (PMID 32150979, 2020). "Some of these tools have been promising in modulating STAT3/5 signaling and inhibiting tumor cell growth." (PMID 31963765, 2020). "Consistently, p-STAT3 expression was positive in tumor tissues from 67/86 HCCs (77.9%) and increased clearly in tumor tissues compared to adjacent liver tissues in 54/86 HCCs (62.8%)." (PMID 31942180, 2020). "RT-PCR analyses also confirmed that anti-tumor effects by astaxanthin were due to the suppression function of STAT3 and the related pathway gene." (PMID 32784629, 2020). "The activated STAT3 signaling pathway initiates the transcription process, including the expression of PD-L1, which in turn enhances tumor immunosuppression." (PMID 33363013, 2020).
tumor (continued). "We aimed to detect clusters that are associated with STAT3 expression and to compare them with clusters correlated to clinical traits, such as BCR, tumor grading, and staging." (PMID 32323921, 2020). "For example, administration of Stat3 reduces skeletal metastatic tumor growth and decreases skeletal tumor size, and CXCL5-deficient mice inhibit tumor progression, providing a clue for designing additional successful therapies." (PMID 32346605, 2020). "All these studies showed that STAT3 played an important role in tumor microenvironment-induced aggressive behaviors, which made STAT3 a promising target in the radiorensitization of cancers." (PMID 32733808, 2020). "On the contrary, corosolic acid inhibits the M2 polarization of macrophages and tumor cell proliferation by blocking both STAT3 and nuclear factor (NF)-κB activation." (PMID 32640667, 2020). "In breast cancer, the interaction of collagen I with DDR1 expressed by tumour cells leads to the induction of stemness-like signalling through the activation of STAT3, which is crucial to mediate the metastatic outgrowth." (PMID 33037194, 2020). "The expression of a subset of genes is associated with CSCs, including markers such as Lgr5, CD133, and CD44, as well as other genes involved in the acquisition of stemness traits in tumor cells, such as transcription factors Nanog, Stat‐3, and c‐Myc." (PMID 31788944, 2020). "Activated STAT3 (pSTAT3) translocates to the nucleus and participates in the transcription of genes that inhibit apoptosis, and promote tumor cell proliferation and metastasis." (PMID 33173024, 2020). "The ability of STAT3 signaling networks to integrate and promote regulatory roles in both, tumor cells and immune cells suggests that this pathway must act as a signaling node, responding to multiple inputs and regulating different effector outputs." (PMID 33330068, 2020). "STAT3 is constitutively activated by Tyr705 and Ser727 phosphorylation in diverse cancers of either hematopoietic or epithelial origin, and STAT3 prevents apoptosis and enhances tumor cell proliferation and survival after activation 49-51." (PMID 32483468, 2020). "All together, these results firstly suggested that GCAFs promote VM formation and tumor growth in GBC via upregulating NOX4 expression through paracrine IL-6 mediating IL-6/JAK/STAT3 signaling pathway." (PMID 33153467, 2020). "The persistent activation of STAT3 has been found in many tumor cells, such as breast cancer, head and neck cancer, colorectal cancer, hepatocellular carcinoma, renal cell carcinoma, prostate cancer, ovarian cancer and leukemia." (PMID 32679860, 2020). "As a well-known player linking inflammation and cancer, STAT3 is frequently overexpressed in tumor cells or tissues, including GC18–20." (PMID 32041943, 2020). "CURC has recently shown anti-tumor properties, relying on the inhibition of oncogenic/pro-survival STAT-3 and NF-kB-dependent pathways, of the pro-invasive factor Sp-1, of tumor-associated inflammation." (PMID 31991669, 2020). "High expression of PLXNC1 manipulated IL6ST expression at the DNA level and activated tumor-related pathways such as the IL-6/STAT3 pathway." (PMID 32117710, 2020). "In particular, IL‐6 is the primary mediator of inflammation, which is the key to trigger the JAK2/STAT3 pathway, and plays a crucial role in tumor cell proliferation and invasiveness." (PMID 32677756, 2020). "BMAs secrete a large amount of IL-6, which induces EMT in cancer cells through the JAK2/STAT3 pathway and increases the metastatic potential of tumor cells by promoting tumor cell survival through the PI3K/AKT pathway." (PMID 32674405, 2020). "Treatment with the NFκB inhibitor partially reversed the effects observed with STAT3 inhibition regarding both tumor growth and T lymphocyte tumor infiltration." (PMID 33330068, 2020).
tumor (continued). "The STAT3 has both tumor-suppressing and tumor-promoting properties, constituting an active version of Stat3alpha that suppresses transformation in mouse embryonic fibroblast." (PMID 32545625, 2020). "Thetranscription of STAT-3 targeted genes in tumor cells can be blocked by EGFR andSrc (upstream tyrosine kinase inhibitor)." (PMID 32167126, 2020). "S1PR1 is usually considered as an oncogene, since it promotes the proliferation, invasion, and metastasis of tumor cells through the STAT3, PI3K/AKT, and CCR signaling pathway in many types of malignant tumors." (PMID 33628734, 2020). "A similar association was observed in STAT3 Tyr705 phosphorylation, and EMT and ECM enzyme biomarkers in tumor tissues grown from HeLa cells in the mouse model." (PMID 33040485, 2020). "Overall, the results establish a central role for STAT3 in tumor growth and encourage further expedient development of STAT3 pathway inhibitors for clinical use." (PMID 33374980, 2020). "Inhibiting fatty acid oxidation or the ablation of STAT3, increased effector T-cell glycolysis and T-cell numbers, resulting in decreased tumor growth." (PMID 33604295, 2020). "For example, a novel strategy combining STAT3 ASO with TLR9 stimulation (CpG oligonucleotide) has been shown to enhance the anti-tumor immunity and overcome tumor immune tolerance in prostate cancer." (PMID 32972405, 2020). "Moderate ROS levels can support the survival of cancer cells through the activation of signaling pathways, such as STAT3, which contribute to tumor growth." (PMID 33003453, 2020). "Silencing SIRT2 significantly suppressed tumor angiogenesis by inhibiting the STAT3/VEGFA signaling pathway in CRC cells." (PMID 31974361, 2020). "Collectively, these studies provided evidence that increased STAT3 activation within tumor cells promotes tumor development while increased STAT3 activation within normal lung epithelial cells induces cellular transformation." (PMID 32365499, 2020). "Specifically, TLR9 promoted PD-L1 transcriptional expression by enhancing STAT3 Tyr705 phosphorylation, resulting in tumor cell immune escape." (PMID 32483468, 2020). "Taken together, these results indicate STAT3 inhibits the ability of the CD103+ cDC1 vaccine to induce tumor-antigen specific CD8+ T cell- and Th1 cell-mediated immunity in the murine breast TME and TdLNs." (PMID 31947933, 2020). "To study if stromal IL6 was activating the canonical JAK/STAT pathway in the tumor cells, we next evaluated the activation of STAT3 by treating with IL6." (PMID 33177492, 2020). "In previous studies of CPT and BRCA, CPT and its synthetic derivatives were used as STAT3 inhibitors to induce tumor cell apoptosis in the BRCA cells MDA-MB-231." (PMID 33505309, 2020). "Inhibited JAK1,2/STAT3 signalling pathway activation was also confirmed in EGFR-TKI-treated NSCLC tumour tissues." (PMID 31892990, 2020). "Persistent STAT3 activation in malignant cells stimulates proliferation, survival, angiogenesis, invasion, and tumor-promoting inflammation." (PMID 33053804, 2020). "The previous studies from others and our group have shown that STAT3 pathway is predominantly responsible for the activation of neutrophils by tumor signals." (PMID 32477934, 2020). "Tumor angiogenesis and Vascular Endothelial Growth Factorappearance is also due to STAT-3 upregulation." (PMID 32167126, 2020). "Crucially, a wealth of information further illustrates that STAT-3 activation contributes to tumor cell survival, proliferation, invasion, and metastasis, and STAT-3 inhibition leads to suppression of the growth of numerous cancers in vitro and in vivo." (PMID 32998376, 2020). "More importantly, we found that HOST2 exert its oncogenic role in TNBC cells via sponging tumour suppressor let-7b and miR-1266 to upregulate STAT3 signaling pathway." (PMID 32248842, 2020). "The expression of p-STAT3 protein located mainly in nucleus of tumor cells, while there was also detectable p-STAT3 protein in cytoplasm of tumor cells." (PMID 31942180, 2020).
tumor (continued). "In conjunction with INCB054329, an inhibitor of bromodomain and extra-terminal motif proteins, itacitinib inhibited STAT3 activation and tumor growth in MM cell lines and murine models." (PMID 33521321, 2020). "Of these three STAT proteins that are most implicated in cancer, many studies have been focused on the roles of STAT3 in tumour development." (PMID 32872372, 2020). "STAT3 is the main factor promoting tumor growth by activating CD4+ regulatory T cells, which ultimately suppress CD8+ cytotoxic T cells and enhance tumor growth." (PMID 33050544, 2020). "Inhibition of the JAK2/STAT3 signal transduction pathway is expected to be an effective way to inhibit tumor growth and promote tumor cell apoptosis." (PMID 33330321, 2020). "In cutaneous T cell lymphoma (CTCL), STAT3/5-dependent IL-9 overexpression promotes tumor cell survival." (PMID 32228589, 2020). "One of the receptors responsible for activation of STAT3 is the receptor of interleukin-6 (IL-6), a pleiotropic cytokine highly produced in the tumour-baring host." (PMID 32779712, 2020). "The stages of carcinogenesis, such as tumor initiation and tumor progression, areenhanced by irregularities in the STAT-3 signaling pathway." (PMID 32167126, 2020). "Studies in preclinical cancer models of solid tumors collectively show that small molecule JAK inhibitors inhibit activation of STATs, particularly STAT3, in conjunction with inhibition of proliferation and tumor growth." (PMID 33521321, 2020). "Our results indicate an inhibitory role for STAT3 in CD103+ cDC1-mediated anti-tumor immunity, including STAT3-dependent suppression of cDC1 maturation and IFN-γ+ T cell responses." (PMID 31947933, 2020). "Accumulated evidence demonstrated that constitutively activated STAT3 is observed in various types of tumor-derived cell lines and tumor tissues, including diverse solid and hematologic cancers." (PMID 32183406, 2020). "When IL-17 binds to IL-17 receptor-bearing tumour cells, it stimulates IL-6 production that is highly important for STAT3 pathway activation." (PMID 32863742, 2020). "Overexpression of TRIM14 in CRC cells via increased STAT3 phosphorylation induced the expression of tumor relevant target genes of STAT3 including MMP-2, MMP-9 and vascular endothelial derived growth factor (VEGF)." (PMID 33066016, 2020). "Consistent with our results, persistently activated STAT3 in both host cells and tumor cells suppresses the inflammation response and promotes the transformation of immunosuppressive immune-cells." (PMID 33288772, 2020). "Phosphorylation can activate STAT3, resulting in its translocation to the nucleus to regulate gene expression, further enhancing tumor angiogenic and invasive capability." (PMID 33194731, 2020). "Via the STAT3 pathway, this transformation triggers TAMs to enhance angiogenesis and tumor cell invasion." (PMID 32973662, 2020). "STAT3 expressed by the tumor cells further enhances IL-6 secretion by the myeloid cells via increased expression of NF-κB in these inflammatory cells, thus creating a positive feedback loop." (PMID 33143283, 2020). "Accumulating evidence demonstrates that STATs play a major role in the process of tumor formation, especially STAT3." (PMID 32784629, 2020). "The production of pro-tumorigenic cytokines including IL-6, which induces STAT3 activation in hepatocytes, eventually promotes compensatory proliferation in hepatocytes that have escaped cell death, and subsequently, tumor development." (PMID 32363190, 2020). "Thereafter, IL-6 activates the signal transducer and activator of transcription 3 (STAT3) pathway in immune cells, stromal cells and tumor cells, which supports immune escape of cancer cells." (PMID 32230983, 2020). "STAT3, thus, plays an extremely important role in the various processes involved in development and progression of the tumor." (PMID 32283655, 2020).